MALSU1 (mitochondrial assembly of ribosomal large subunit 1)
Description:
Required for normal mitochondrial ribosome function and mitochondrial translation. May play a role in ribosome biogenesis by preventing premature association of the 28S and 39S ribosomal subunits (Probable). Interacts with mitochondrial ribosomal protein uL14m (MRPL14), probably blocking formation of intersubunit bridge B8, preventing association of the 28S and 39S ribosomal subunits (Probable). Addition to isolated mitochondrial ribosomal subunits partially inhibits translation, probably by interfering with the association of the 28S and 39S ribosomal subunits and the formation of functional ribosomes (Probable). May also participate in the assembly and/or regulation of the stability of the large subunit of the mitochondrial ribosome. May function as a ribosomal silencing factor (Probable).
Synonyms: C7orf30; mtRsfA
Tractability: Small molecule: a structure with a bound ligand is known. PROTAC: ubiquitination databases record sites on it.
Gene: Protein-coding gene on chromosome 7 (23,298,739 to 23,311,729, forward strand). Ensembl gene ENSG00000156928.
Subcellular location: Mitochondrion matrix
Subcellular location (Human Protein Atlas): Mitochondria
Pathways (Reactome):
Metabolism of proteins: Mitochondrial ribosome-associated quality control
Gene Ontology:
Molecular function: mitochondrial large ribosomal subunit binding; protein binding; ribosomal large subunit binding
Biological process: mitochondrial large ribosomal subunit assembly; negative regulation of mitochondrial translation; ribosomal large subunit biogenesis; negative regulation of ribosome biogenesis; negative regulation of translation
Cellular component: mitochondrial matrix; mitochondrion
Genetic constraint (gnomAD): Loss-of-function variants: 19 observed, 18.71 expected, observed/expected ratio (o/e) 1.02, 90% interval 0.71 to 1.49. The synonymous counts are far from expectation, so gnomAD's model fits this gene poorly and the ratio says little. Missense variants: 367 observed, 303.36 expected, observed/expected ratio (o/e) 1.21, 90% interval 1.11 to 1.32. Synonymous variants: 148 observed, 113.96 expected, observed/expected ratio (o/e) 1.3, 90% interval 1.13 to 1.49.
Homologues: Orthologues: chimpanzee MALSU1 (99% identical), macaque MALSU1 (94% identical), dog MALSU1 (75% identical), pig MALSU1 (75% identical), rabbit MALSU1 (73% identical), guinea pig MALSU1 (72% identical), mouse Malsu1 (71% identical), rat Malsu1 (70% identical), tropical clawed frog malsu1 (46% identical), zebrafish malsu1 (35% identical), Drosophila melanogaster CG9166 (25% identical).
Diseases named in the same sentence as MALSU1 in open-access papers:
MALSU1 is named in the same sentence as 4 diseases in open-access papers, as found by Europe PMC text mining. Sharing a sentence is not in itself a finding about the gene and the disease. The quoted sentences say what the papers report.
lung carcinoma (1 paper, 2022). "H1975 human lung cancer cells expressing control sgRNA or sgRNA against c14orf2, MALSU1, or TMEM261 were then compared for differences in respiratory chain function." (PMID 36137002, 2022).
tumor (2 papers, 2022). "Interestingly, compared to control sgRNA, MALSU1 silencing was associated with increased metastatic BLI signal relative to the primary tumor." (PMID 36137002, 2022). "Specifically, expression of glycolysis pathway genes, while increased in vitro, was significantly reduced in MALSU1 sgRNA cells grown in vivo, supportive of the concept that tumor cells grown in vivo optimize respiratory function." (PMID 36137002, 2022). "In TMEM261-silenced tumors, primary tumor growth was suppressed, which contrasts with MALSU1-silenced tumors." (PMID 36137002, 2022). "TMEM261-silenced cells produced a smaller primary tumor compared to control cells, but silencing either MALSU1 or TMEM261 resulted in increased metastasis signal relative to the primary tumor." (PMID 36137002, 2022). "We validated the mRNA expression levels of the 4 ferroptosis-related genes (ZNF566, TMEM150C, ENDOU, MALSU1) in the tumor tissue and adjacent tissue of 10 HNSCC patients by RT-qPCR." (PMID 36531250, 2022). "c14orf2, MALSU1, and TMEM261 were top CRISPRi ATP-modulating hits that each underlie respiratory chain dysfunction, severely impacting ATP production as well as in vivo tumor growth." (PMID 36137002, 2022). "In summary, individual silencing of either MALSU1 or TMEM261 each significantly impacted tumor progression in vivo, with differential effects on primary and metastatic progression, revealing that tumors in different locations differ in their metabolic requirements." (PMID 36137002, 2022). "TMEM261 silencing was associated with the most severe reduction in respiration and ATP among all the mito-respiratory hits, and the suppression of primary tumor growth (as compared to control tumors and MALSU1-silenced tumors) correlates with reduced respiratory ATP." (PMID 36137002, 2022). "We focused on c14orf2, MALSU1, and TMEM261, which encode mitochondrial proteins that were previously identified as strong low ATP hits under respiratory conditions; these genes are among the strongest growth repressive hits in both the flank and orthotopic tumor growth screen." (PMID 36137002, 2022). "In vivo, the effects of MALSU1 and TMEM261 silencing on tumor growth differed while demonstrating that metastasis formation relative to primary tumor was promoted." (PMID 36137002, 2022). "c14orf2, MALSU1, and TMEM261 have no known roles in supporting tumor growth; however, these data provide evidence that their functions promote tumor growth and collectively suggest that mitochondrial genes are necessary for in vivo tumor growth." (PMID 36137002, 2022).
MALSU1 also shares sentences with these, for which no sentence is quoted: esophageal cancer (1 paper); melanoma (1).